IRAK1 (interleukin 1 receptor associated kinase 1)
Diseases named in the same sentence as IRAK1 in open-access papers (continued):
Sharing a sentence is not in itself a finding about the gene and the disease.
infection (69 papers, 2008 to 2025). The state of being infected such as from the introduction of a foreign agent such as serum, vaccine, antigenic substance or organism. "Many downstream effector genes such as Interleukin-1 receptor-associated kinase 1 (Irak1), Transcription factor (Jun), Mavs [Ips-1], Mitogen-activated protein kinase kinase 7 (Map3k7[Tak1]) were downregulated during infection." (PMID 36851549, 2023). "Pathway-analysis suggested that genetic variation in the IRAK1-pathway is also involved in this infection susceptibility." (PMID 33947878, 2021). "A recent study found that, upon infection, Dectin-1 can modulate interleukin-1 receptor-associated kinase 1 (Irak1) and receptor-interacting protein 2 (Rip2), which are the key adaptor proteins in the TLR and Nod-like receptor signaling pathways, respectively." (PMID 31687150, 2019). "We hypothesized that the susceptibility to infection could be caused by a hyperinflammatory immune response due to increased canonical NF-κB signaling because of IRAK1 overexpression." (PMID 36319802, 2023). "Infection with rhinovirus has been shown to promote degradation of the signaling molecule interleukin 1 receptor associated kinase 1 (IRAK1), leading to reduced epithelial production of CXCL8 and impaired neutrophil chemotaxis in response to non-typeable Haemophilus influenzae." (PMID 35563722, 2022). "Therefore, patients treated with an IRAK1-specific inhibitor might have a reduced risk for infection by microbial pathogens than patients treated with an IRAK4 inhibitor." (PMID 27807192, 2016). "It is secreted into the cytoplasm during infection, where it interacts with the IRAK-1-Toll-interacting protein to disassociate it from IL-1R-associated kinase-1 (IRAK)." (PMID 40141253, 2025). "IRAK1 overexpression was noted during infection of GI.1 and GI.2 (2.1-fold change, p = 0.01 vs. control and 2.6-fold change, p = 0.001 vs. control)." (PMID 39273479, 2024). "Protein levels of Rig-I or IRAK1, respectively were reduced by 60–80% at the time point of infection compared to scramble transfected control cells." (PMID 35140216, 2022). "In contrast, although IRAK1 levels were lowered after 8 h post infection with L. pneumophila bacteria and after 3 h incubation with Lp-EVs, this was independent of RsmY." (PMID 35140216, 2022). "Our data indicate that the SINV CP protein reduces the dose responsiveness of IRAK1-dependent TLRs during ectopic expression and infections of tissue culture models." (PMID 33673546, 2021). "During infection to EBV, TLR7/8 (Toll-like receptor 7/8) signaling elevated PD-L1 through MyD88 (myeloid differentiation primary response 88) and IRAK1/4 (interleukin 1 receptor-associated kinase 1/4) signaling." (PMID 34503236, 2021). "Analysis of mRNA levels revealed a significant decrease in expression of the miR‐146a/b direct target gene Irak1 during RV‐A1b infection and increased Card10 expression in the PBS treatment group in Mir146a/b−/− mouse lungs compared to wt mice." (PMID 34185416, 2021). "IL-1β, a potent pro-inflammatory cytokine facilitating host defense responses to infection, was used to activate IRAK1." (PMID 34906138, 2021). "Knockdown of the transcription of either MYD88 or IRAK1 abolished the production of infection-induced proinflammatory cytokines and chemokines, such as interleukin 8 (IL-8), IL-1ꞵ, and IL-2." (PMID 34933448, 2021). "Taken together, our data demonstrate the importance of the interaction between the alphavirus CP and IRAK1 proteins on IRAK1-dependent signaling in a cellular model of infection." (PMID 33673546, 2021). "We next tested the function of the PDHB inhibitor oxythiamine (OT), as well as its combination with IRAK1/4-Inh, in S. flexneri ΔvirG infection." (PMID 34933448, 2021).
infection (continued). "Taken together, our results corroborated that the IL-1β-induced degradation of IRAK-1 in lung epithelial cells can negatively impact IL-8 expression upon infection by L. pneumophila, suggesting its crucial role in regulating hypo-responsiveness." (PMID 28931863, 2017). "Of note, infection with S. pneumoniae or S. pneumoniae in combination with B7-H3 led to reduced protein expression of IRAK1." (PMID 28141831, 2017). "As THP-1 cells responded differently to LTA or LPS as a first stimulus before infection with L. pneumophila, we analyzed IRAK-1 protein expression after treatment with these TLR ligands." (PMID 27105429, 2016). "The infection of OMV pre-treated cells further decreased IRAK-1 protein levels more than L. pneumophila infection alone." (PMID 27105429, 2016). "Another intriguing possibility comes from work showing that EV71 modulates the levels of TRAF6 and IRAK1 during infection." (PMID 26437794, 2015). "In subsequent experiments, we treated macrophages with IRAK1/4 inhibitor or anti-CR3 mAb before infection with Mtb." (PMID 24039915, 2013). "Following infection, Interleukin-1 receptor-associated kinase 1 (IRAK-1) expression is diminished in LCMV-ARM- but not LCMV-WE-infected cells, which indicates it is likely involved in the LCMV-ARM NF-κB activation." (PMID 38675975, 2024). "Whole lung tissue was collected 24 h after infection and processed for RT-qPCR to evaluate for relative gene expression of proinflammatory genes IRAK1, TRAF6, NF-κB, IL-6, MIP-2 (murine IL-8 analog), IL-1β, and TNFα as these cytokines outline the pathway along which miR146a functions." (PMID 37765178, 2023). "Thus, the SINV CP protein delivered as part of the nucleocapsid core is capable of diminishing the IRAK1-dependent sensing of ssRNA PAMPs during the early stages of infection." (PMID 33673546, 2021). "Activated IRAK1 signal by infection promotes accumulation of Aβ and chronic inflammation." (PMID 34094639, 2021). "Accordingly, we may reasonably conclude that, in addition to the numerous other changes to the cellular environment, IRAK1-dependent signaling during the later stages of infection is impacted by the SINV CP protein." (PMID 33673546, 2021). "To test whether the SINV CP protein can negatively impact IRAK1-dependent signaling in an entry model of infection, we utilized a co-exposure system to assess the dose responsiveness of the TLR7 receptor in the presence of SINV particles." (PMID 33673546, 2021). "To assess whether IRAK4 and TRAF6 are functional targets for Mtb to the induction of IL-8 production, we incubated the macrophages with an IRAK1/4 inhibitor prior to the infection." (PMID 31871425, 2019). "As a negative regulator involved in innate immunity, along with induction of kinase activity of IRAK1/4 during infection, IRAK-M interacts with IRAK4 to induce transcription of downstream inhibitors such as A20, IĸBα, SOCS-1 and SHIP, to prevent radical immune pathology of the host." (PMID 28835201, 2017). "However, infection with S. pneumoniae or S. pneumoniae in combination with B7-H3 resulted in substantially reduced protein expression of IRAK1." (PMID 28141831, 2017). "Furthermore, LPS/IFN-γ pre-treated cells showed a higher IRAK-1 protein expression than OMV pre-treated cells following infection." (PMID 27105429, 2016). "The siRNA-mediated knockdown of IRAK-1 led to 50% reduced mRNA and protein levels in comparison to scramble (scr) transfected control cells at the time point of infection, which remained stable during the time course of the infection (24 h p.i.: 57% reduction; 48 h: 57% reduction)." (PMID 27105429, 2016).
infection (continued). "Either DEK or IRAK1 knockdown alone could induce apoptosis as expected (8–10 fold over control), but the combined effect of IRAK1 shRNA with AdDEKsh infection was greater than that of the respective control cells (20-fold)." (PMID 26527316, 2015). "RV39 infection decreased IRAK-1 levels as early as 4 h post-infection." (PMID 23055935, 2012). "Reduced IRAK-1 was also observed in mice infected with RV 48 h post-infection." (PMID 23055935, 2012). "Therefore, we hypothesized that the infections may be triggered by a strong acute phase response due to IRAK1 overexpression and subsequently increased canonical NF-κB signaling." (PMID 36319802, 2023). "However, in the lung tissue of pigs infected experimentally with influenza virus (H1N2), the level of miR-146 was significantly decreased the first day after infection, which may affect the expression of IRAK1, STAT1, and TLR2." (PMID 36142450, 2022). "After infection, c-Jun and c-Fos bind to the AP-1 binding sites in the miR-21 promoter and evoke AP-1 mediated miR-21 induction, leading to the silencing of MyD88 and IRAK1, which play a major role in the initiation of the antiviral response in host cells and increased virus production." (PMID 23633945, 2013). "In contrast, PC3 and LNCaP cells, exhibiting hypomethylated IRAK1-DMR and high endogenous IRAK1-mRNA levels, responded with strong activation of IRAK1-expression to UTI89 infection." (PMID 36226067, 2022). "Four hours after infection of PCa cell lines with uropathogenic E. coli UTI89 at a multiplicity of infection of 10, PC3 and LNCaP cells had a 2-fold increase of IRAK1 expression." (PMID 36226067, 2022). "Following the validation of the SINV CP–IRAK1 interaction using BiMC, we hypothesized that the CP–IRAK1 interaction might be a means by which alphaviruses interfere with IRAK1-dependent signaling during infection to evade the induction of an antiviral innate immune response early during infection." (PMID 33673546, 2021). "Therefore, in addition to be an early mechanism by which the sensing of viral PAMPs by the IRAK1-dependent TLRs may be manipulated, ongoing CP protein expression represents a means by which IRAK1-dependent processes are blunted during the later stages of infection." (PMID 33673546, 2021). "To note, mRNA level of IRAK1 significantly decreased during HSV-1 infection in THP-1, probably depending on related increase of miR146a level at late stage of infection." (PMID 30914680, 2019). "According to these data, we analyzed the expression at transcriptional level of IRAK1 in THP-1 and DN-IκBα THP-1 cells infected with HSV-1 at indicated time post infection." (PMID 30914680, 2019). "Infection with RV39 and UV-RV39 each decreased IRAK-1 protein levels significantly 24 h after incubation." (PMID 23055935, 2012). "The change pattern of transcription levels of MyD88, IRAK-1, and TRAF-6 of macrophage was consistent with its response to pRBC lysate after infection with either strain." (PMID 22463100, 2012). "Here we show that upon infection, SHP-1 rapidly binds to IRAK-1, completely inactivating its intrinsic kinase activity and any further LPS-mediated activation as well as MØ functions." (PMID 19104650, 2008). "Seven differentially expressed genes (DDX58, STAT1, MX1, IRAK1, MAPK11, RELA, and ICAM1) were randomly selected and quantified using qRT-PCR to validate the differential expression observed in A549 cells using RNA-Seq across varying infection time points." (PMID 38673764, 2024). "The expression pattern of anti-inflammatory miRNAs 146a and 124, and the inflammatory mediator TRAF6 and IRAK1, suggest an acute increase in inflammation in the early stages of infection, followed by negative feedback." (PMID 37376550, 2023).
infection (continued). "In human nasal epithelial cells (hNECs), after infection with influenza H3N2 virus, miR-146a was induced, regulating TRAF6 expression but not IRAK expression in the nasal epithelium; in contrast, it targeted IRAK1 in the lower airway." (PMID 36142450, 2022). "Consistent with our results, another study performed an analysis of phosphorylated sequences within host cells and predicted activation of IRAK4 within 15 min of infection of Vero cells with SARS-CoV-2, and also revealed that a different inhibitor of IRAK1/4 impaired SARS-CoV-2 infection." (PMID 34857794, 2021). "In contrast, infection neither affected expression of key activators of the TLR pathway (IRAK1, MYD88, and RELA) nor RELB, a key element pivotal for DC differentiation, maturation, and MHC Class I-restricted presentation." (PMID 32582184, 2020). "As would be expected, TRAF6 and IRAK1 were decreased in LV-Omp25-infected cells compared to the cells infected with LV-Blank 24 h post-infection, with no change for IRAK2." (PMID 29387067, 2017). "However, significant alterations in the expression pattern of specific target genes (TRAF6, IRAK1 and IRAK2) were observed only after 32 hours of infection." (PMID 25083878, 2014). "The transcriptional levels of MyD88, IRAK-1, and TRAF-6 were significantly increased in mice infected with either P. yoelii 17XL or 17XNL compared to control mice at one, three and five days post-infection." (PMID 22463100, 2012). "Our results indicated that unlike LPS stimulation per se that activates IRAK-1, infection with Leishmania rendered IRAK-1 activation refractory to this TLR4 agonist." (PMID 19104650, 2008). "LCMV-WE infection of murine macrophages did not result in co-localization of viral NP with IRAK-1." (PMID 38675975, 2024). "DU145 cells, exhibiting hypermethylated IRAK1-DMR and low IRAK1-expression, reacted with 4-fold increased IRAK1-expression upon combined treatment with 5-aza-2-deoxycytidine and trichostatin A, and were unresponsive to infection with the uropathogenic Escherichia coli strain UTI89." (PMID 36226067, 2022). "We were not able to observe an obvious peak of phospho-IRAK1 at 2 h post-infection." (PMID 24278275, 2013). "However, transcription of intracellular signalling molecules MyD88, IRAK-1, and TRAF-6 was significantly up-regulated in peritoneal macrophages from mice infected either with P. yoelii 17XL or P. yoelii 17XNL at one, three and five days post-infection." (PMID 22463100, 2012). "Interestingly, although P01A and P01B had Xq28 duplications that clearly included IRAK1, they did not have the recurrent infections reported in some other patients." (PMID 22909152, 2012). "Importantly, the data shown in this study demonstrate that a permissive infection is not required for the perturbation of IRAK1-dependent signaling, suggesting that bystander cells which are not actively infected may exhibit disrupted signaling profiles." (PMID 33673546, 2021). "TRAF6 was found to interact with IRAK1 and TAK1 after infection with different strains, but the binding of TRAF6 to IRAK1 or TAK1 was not different in RAW264.7 cells infected with rMS::pMV261 or rMS::pMV261-Rv0927c." (PMID 34531869, 2021). "Moreover, IRAK1/4-Inh, OT, and their combination each significantly reduced host cell death and intracellular wild-type pathogen survival, indicating that the effects of these small-molecule inhibitors was not restricted to infection with the mutant strain S. flexneri ΔvirG." (PMID 34933448, 2021). "IRAK1 protein levels showed no change in Meth treated vs. untreated cells, but decreased expression in HIV+ and HIV+Meth treated cells 2 days post infection." (PMID 32117283, 2020).
infection (continued). "Therefore, in the absence of infection, Tollip probably maintains immune cells in a resting state and terminates IL-1R- and TLR-induced inflammatory pathways via the suppression of IRAK1 activity." (PMID 25269519, 2014).
hematological malignancies (9 papers, 2015 to 2024). "Interleukin 1 receptor associated kinase 1 (IRAK1) is an emerging therapeutic target in hematologic malignancies, and it has been suggested that IRAKs participate in regulatory interactions with FADD." (PMID 38412862, 2024). "We chose to probe the role of the IRAK1 serine/threonine kinase, a driver of inflammatory pathways in hematological disease, based on its function as a central signaling hub in the cytoplasm, and as a targetable molecule in MDS and AML." (PMID 26527316, 2015). "IRAK1/4 inhibitor was originally developed for autoimmune and inflammatory diseases, and was effective in-vitro and in-vivo in hematological malignancies (MDS, AML, DLBCL) that overactivate the IRAK1 pathway, albeit to a lesser extent." (PMID 26068967, 2015). "In addition, recent clinical trials of IRAK1/4-related inhibitors in RA and hematologic diseases have also been conducted, indicating the effectiveness and feasibility of IRAK1/4 inhibitors in inflammation and tumor-related diseases." (PMID 35699749, 2022). "As such, constitutive activation of the IL-1R pathway and its fundamental signal transducer proteins (interleukin-1 receptor-associated kinase 1, IRAK1; myeloid differentiation primary response 88 protein, MYD88) has been demonstrated in several hematological malignancies." (PMID 33530653, 2021).
inflammation (8 papers, 2016 to 2023). Aberrant reaction of the microcirculation characterized by movement of fluid and leukocytes from the blood into extravascular tissues. "IRAK1 plays a major function in mediating the release of TNF-α, MIP-2, CXCL1, and IL-17 cytokines along with the MAPK pathway in airway inflammation, which leads to alveolar wall thickening and accumulation of collagen fibers." (PMID 36678340, 2023). "Furthermore, similar to the effects of the miR-146a mimic, IRAK-1 siRNA significantly inhibited the expression of HG-stimulated VCAM-1/ICAM-1 gene expression and THP-1 adhesion to HAECs, indicating that HG-induced endothelial inflammation was mediated partially through IRAK-1." (PMID 28824448, 2017).
bacterial infection (7 papers, 2012 to 2022). "As a potential strategy to control intracellular bacterial infection by targeting host factors, we tested the functions of corresponding small-molecule inhibitors IRAK1/4-inhibitor I (IRAK1/4-Inh) and ginsenoside compound K (CK)." (PMID 34933448, 2021). "For example, miR-146a can modulate the innate immune response to bacterial infection by targeting the TNF receptor associated factor 6 (TRAF6) and interleukin receptor associated enzyme I (IRAK1)." (PMID 25749476, 2015). "miR-146a, for example, regulates the innate immune response to bacterial infection, targeting TNF receptor-associated factor 6 (TRAF6) and Interleukin-1 receptor-associated kinase 1 (IRAK1), while miR-150 regulates the production of mature B cells." (PMID 23472090, 2013). "Together, these results indicate that RV-induced reductions in IRAK-1 may attenuate chemokine production in response to secondary bacterial infection via desensitization of MyD88-dependent TLR signaling." (PMID 23055935, 2012). "The decisive role of DNA methylation in IRAK1-DMR in IRAK1 activation was analyzed and confirmed in cell culture experiments using bacterial infection." (PMID 36226067, 2022).
kidney (3 papers, 2016 to 2025). "Our patients carrying these IRAK1 changes tended to have more severe clinical features, aligning with earlier studies linking IRAK1 variants to diffuse cutaneous forms and interstitial lung involvement." (PMID 40843700, 2025).